ILK (integrin linked kinase)
Diseases named in the same sentence as ILK in open-access papers (continued):
Sharing a sentence is not in itself a finding about the gene and the disease.
kidney diseases (8 papers, 2012 to 2025). "Further studies will be necessary to elucidate the underlying mechanisms by which ILK depletion affects autophagy in the context of renal disease." (PMID 40076489, 2025). "Our study provides novel evidence implicating ILK in mitochondrial dysfunction during kidney injury, underscoring its potential role as a therapeutic target for preserving mitochondrial function in renal disease." (PMID 40076489, 2025). "In this study, we explore the relationship between ILK, mitochondrial function, and autophagy in the context of renal disease." (PMID 40076489, 2025). "We studied the role of ILK and its downstream regulations in renal damage and mitochondria function both in vivo and vitro, using a folic acid (FA)-induced kidney disease model." (PMID 40076489, 2025). "Integrin-linked kinase (ILK) can modulate TGF-β1-induced glomerular mesangial cell (GMC) injury, which is a prominent characteristic of renal pathology in kidney diseases." (PMID 25142208, 2014). "Therefore, we propose ILK as a potential therapeutic target to preserve renal mitochondrial homeostasis in kidney disease." (PMID 40076489, 2025). "Consistent with our findings, previous studies have described that ILK can inhibit autophagy through the ILK-downstream mediator AKT pathway while also promoting autophagy under stress conditions via AMP-activated protein kinase (AMPK) activation in various kidney diseases." (PMID 40076489, 2025). "While our study suggests that ILK overexpression influences both mitochondrial dysfunction and autophagy, future research is needed to determine whether ILK directly regulates mitophagy and its implications for renal disease progression." (PMID 40076489, 2025). "ILK plays an important role in the interface between TGF-β1, ECM, the actin-based cytoskeleton and the cellular phenotype in kidney diseases." (PMID 25142208, 2014). "Remarkably, gene mutations in the integrin linker proteins (paxillin and talin), signaling kinases focal adhesion kinase (FAK), integrin-linked protein kinase (ILK), complex protein PINCH, and kindlin-2 have not been reported to be causative in human kidney disease." (PMID 32708597, 2020). "ILK, a cytoplasmic-binding serine/threonine protein kinase, is physically connected to the actin cytoskeleton and actin-binding protein CH-ILKBP, which is an important step in the development and progression of glomerular failure observed in several kidney diseases." (PMID 25142208, 2014). "However, to the best of our knowledge, no study has ever reported whether ILK could be useful as a CKD biomarker despite its elevated expression levels observed in a wide variety of renal diseases." (PMID 38734696, 2024).
bacterial infection (3 papers, 2013 to 2024). "In this report we have added to our understanding of the role of ILK in intestinal pathophysiology, specifically in the setting of bacterial infection." (PMID 24024606, 2013).
cardiovascular diseases (3 papers, 2022). "As a major regulator of cytoskeletal remodeling, ILK pathway remains of a major interest in various cardiovascular disease." (PMID 35310970, 2022).
neurodegenerative disease (2 papers, 2015 to 2020). A disorder of the central nervous system characterized by gradual and progressive loss of neural tissue and neurologic function. "Inhibitors of ILK have been found to increase Tau protein hyperphosphorylation (a hallmark of neurodegenerative disorders) through activation of GSK3β, highlighting the important role of ILK in the etiology of neurodegenerative disease." (PMID 26305322, 2015). "In neurodegenerative diseases (e.g., Alzheimer’s disease and Parkinson’s disease) characterized by learning and memory deficits, ILK-related mechanisms are compromised." (PMID 26305322, 2015). "Some preliminary studies from our laboratory suggest that the interaction of ILK with glutamate receptors is of relevance in neurodegenerative diseases because changes in ILK expression can produce changes in downstream signaling molecules as well as changes in its scaffolding property." (PMID 26305322, 2015).
brain disorder (1 paper, 2015). A disease affecting the brain or part of the brain. "Considering that EE is beneficial to many brain disorders, ILK is a potentially important therapeutic target that merits further study." (PMID 26095336, 2015).
colonic polyps (1 paper, 2003). "In our previous study, we demonstrated that overexpression of ILK in colonic polyps coincided with an increase in the immunoprecipitated ILK MBP phosphotransferase activity." (PMID 12771992, 2003).
hematologic malignancies (1 paper, 2022). "Recent findings detailing the contribution of ILK to therapeutic resistance and the importance of ILK as a potentially therapeutically tractable vulnerability in both solid tumors and hematologic malignancies are discussed." (PMID 35804980, 2022).
ILK also shares sentences with these, for which no sentence is quoted: lymphoma (4 papers); astrocytomas (3); Familial exudative vitreoretinopathy (3); Ventricular hypertrophy (3); asthma (2); benign tumors (2); chronic kidney disease (2); endometrial cancer (2); esophageal cancer (2); Hyperinsulinemia (2); inflammation (2); inflammatory bowel disease (2); metastasis (2); oligodendroglioma (2); renal failure (2); acute lymphoblastic leukemia (1); acute myocardial infarction (1); adenocarcinoma (1); adenoma (1); adenomyosis (1); aortic stenosis (1); arteriosclerosis (1); autoimmune uveitis (1); autosomal dominant polycystic kidney disease (1); basal cell carcinoma (1); carcinoma of the oesophagus (1); cholestasis (1); cobblestone lissencephaly (1); colorectal adenoma (1); congenital cataracts (1).
A further 43 diseases each share a sentence with ILK in 1 paper.